RGS13 (regulator of G protein signaling 13)
Description:
Inhibits signal transduction by increasing the GTPase activity of G protein alpha subunits thereby driving them into their inactive GDP-bound form. Binds to both G(i)-alpha and G(q)-alpha (By similarity).
Tractability: Antibody: its Gene Ontology location is reachable by antibodies, with high confidence. PROTAC: ubiquitination databases record sites on it.
Gene: Protein-coding gene on chromosome 1 (192,636,061 to 192,660,311, forward strand). Ensembl gene ENSG00000127074.
Pathways (Reactome):
Signal Transduction: G alpha (i) signalling events; G alpha (q) signalling events
Gene Ontology:
Molecular function: protein binding; GTPase activity
Biological process: G protein-coupled receptor signaling pathway; negative regulation of G protein-coupled receptor signaling pathway
Cellular component: cytoplasmic side of plasma membrane; plasma membrane; cytosol; nucleus
Genetic constraint (gnomAD): Loss-of-function variants: 6 observed, 12.61 expected, observed/expected ratio (o/e) 0.48, 90% interval 0.26 to 0.94. The upper end of that interval is the gene's LOEUF score, 0.94, which puts it in group 3 of 6, group 1 being the genes least tolerant of losing a copy. Missense variants: 139 observed, 142.82 expected, observed/expected ratio (o/e) 0.97, 90% interval 0.85 to 1.12. Synonymous variants: 39 observed, 44.25 expected, observed/expected ratio (o/e) 0.88, 90% interval 0.68 to 1.15.
Homologues: Orthologues: chimpanzee RGS13 (100% identical), macaque RGS13 (96% identical), dog RGS13 (91% identical), guinea pig RGS13 (91% identical), pig RGS13 (91% identical), rabbit RGS13 (88% identical), mouse Rgs13 (83% identical), rat Rgs13 (82% identical), tropical clawed frog rgs13 (56% identical), zebrafish rgs13b (48% identical), zebrafish rgs13a (45% identical). Paralogues in human: RGS2 (43% identical), RGS1 (42% identical), RGS4 (42% identical), RGS3 (40% identical), RGS8 (39% identical), RGS16 (38% identical), RGS19 (38% identical), RGS21 (38% identical), RGS20 (37% identical), RGS5 (37% identical), RGS18 (36% identical), RGS17 (33% identical), and 11 more.
Diseases named in the same sentence as RGS13 in open-access papers:
RGS13 is named in the same sentence as 13 diseases in open-access papers, as found by Europe PMC text mining. Sharing a sentence is not in itself a finding about the gene and the disease. The quoted sentences say what the papers report.
allergic asthma (2 papers, 2021 to 2023). A asthma with a basis in a pathological type I hypersensitivity reaction. "Recent studies have shown that IL‐38 could inhibit the activation of intracellular STAT1/3, ERK1/2, P38 MAPK, and NF‐κB signaling pathways, and upregulate the expression of antiallergic response gene RGS13 and host defense‐related gene POU2AF1 in mice with allergic asthma." (PMID 37382260, 2023).
Burkitt lymphoma (1 paper, 2018). A rare form of malignant mature B-cell non-Hodgkin lymphoma. "We confirmed RGS13 expression by RT-PCR in Raji cells, a Burkitt’s lymphoma cell line." (PMID 30308012, 2018).
Insulin resistance (1 paper, 2022). Increased resistance towards insulin, that is, diminished effectiveness of insulin in reducing blood glucose levels. "Finally, the associations of RGS8, RGS13, RGS18, and RGS21 with insulin secretion or insulin resistance need to be further investigated." (PMID 36497154, 2022).
mastocytoma (1 paper, 2015). A localized tumor composed of sheets of mast cells without atypia. "Similarly, increased RGS13 attenuates AKT activation and migration in HMC-1 mastocytoma cells." (PMID 25897806, 2015).
melanoma (1 paper, 2018). A malignant, usually aggressive tumor composed of atypical, neoplastic melanocytes. "RGS13 expression also reduces cAMP production, which plays an important role in melanoma even though genetic alterations in components of this pathway are not commonly found in melanomas." (PMID 28974924, 2018). "Although the molecular events responsible for their activity remain to be defined, the upregulation of PTN, RGS13, and SPARC in black color skin could explain the incidence of melanoma in light coat color horses." (PMID 28974924, 2018).
ovarian carcinoma (1 paper, 2024). A malignant neoplasm originating from the surface ovarian epithelium. "This five-gene signature (RGS11, RGS10, RGS13, RGS4, and RGS3) is overexpressed in ovarian cancer and involved in extracellular matrix–receptor interaction, the TGF-β signaling pathway, the Wnt signaling pathway, and the chemokine signaling pathway." (PMID 39145770, 2024).
cancer (2 papers, 2016 to 2021). A tumor composed of atypical neoplastic, often pleomorphic cells that invade other tissues. "In summary, except for RGS13, the role of the other four genes in cancer was all relatively exact, confirming the reliability and robustness of our 5-gene signature as a LUAD biomarker." (PMID 34249701, 2021).
tumor (2 papers, 2025). "RGS13 is predominantly expressed in macrophages, while RCCD1 is expressed at low levels in various cell types within the tumor microenvironment." (PMID 40161374, 2025). "Analysis of B- and plasma cells (26,156 cells) showed that germinal centre (GC) B-cells (RGS13+, NEIL1+), cycling B-cells (UBE2C+, TYMS+) and naïve B-cells (TCL1A+, IL4R+) were all enriched in HPV+ve tumours compared to HPV-ve tumours, while switched B-cell subsets were found in both." (PMID 39757146, 2025).
RGS13 also shares sentences with these, for which no sentence is quoted: asthma (1 paper); Autoimmunity (1); lupus (1); myasthenia gravis (1); uterine corpus endometrial carcinoma (1).